TIMM22 (translocase of inner mitochondrial membrane 22)
Description:
Essential core component of the TIM22 complex, a complex that mediates the import and insertion of multi-pass transmembrane proteins into the mitochondrial inner membrane. In the TIM22 complex, it constitutes the voltage-activated and signal-gated channel. Forms a twin-pore translocase that uses the membrane potential as external driving force in 2 voltage-dependent steps (By similarity).
Synonyms: TEX4; TIM22; COXPD43
Tractability: Small molecule: a structure with a bound ligand is known. Antibody: UniProt predicts a signal peptide or a membrane-spanning region. PROTAC: ubiquitination databases record sites on it; its protein half-life has been measured.
Gene: Protein-coding gene on chromosome 17 (997,118 to 1,003,671, forward strand). Ensembl gene ENSG00000177370.
Subcellular location: Mitochondrion inner membrane
Pathways (Reactome):
Metabolism of proteins: Mitochondrial protein degradation
Protein localization: Mitochondrial protein import
Gene Ontology:
Molecular function: membrane insertase activity; protein binding; protein transmembrane transporter activity
Biological process: protein insertion into mitochondrial inner membrane; establishment of protein localization to membrane; protein transmembrane transport
Cellular component: mitochondrial inner membrane; mitochondrion; TIM22 mitochondrial import inner membrane insertion complex
Genetic constraint (gnomAD): Loss-of-function variants: 12 observed, 19.49 expected, observed/expected ratio (o/e) 0.62, 90% interval 0.39 to 1. The upper end of that interval is the gene's LOEUF score, 1, which puts it in group 4 of 6, group 1 being the genes least tolerant of losing a copy. Missense variants: 278 observed, 268.46 expected, observed/expected ratio (o/e) 1.04, 90% interval 0.94 to 1.14. Synonymous variants: 107 observed, 104.94 expected, observed/expected ratio (o/e) 1.02, 90% interval 0.87 to 1.2.
Gene-disease validity (ClinGen):
ClinGen rates the evidence that TIMM22 causes each of these diseases.
mitochondrial disease (autosomal recessive): Limited.
Homologues: Orthologues: chimpanzee TIMM22 (99% identical), mouse Timm22 (95% identical), rabbit TIMM22 (95% identical), dog TIMM22 (94% identical), guinea pig TIMM22 (94% identical), pig TIMM22 (93% identical), rat Timm22 (93% identical), tropical clawed frog timm22 (83% identical), zebrafish TIMM22 (74% identical), macaque TIMM22 (73% identical), Drosophila melanogaster CG31229 (45% identical), Caenorhabditis elegans C47G2.3 (39% identical).
Diseases named in the same sentence as TIMM22 in open-access papers:
TIMM22 is named in the same sentence as 11 diseases in open-access papers, as found by Europe PMC text mining. Sharing a sentence is not in itself a finding about the gene and the disease. The quoted sentences say what the papers report.
Sengers syndrome (4 papers, 2018 to 2022). Congenital cataract - hypertrophic cardiomyopathy - mitochrondrial myopathy (CCM) is a mitochondrial disease characterized by cataracts, hypertrophic cardiomyopathy, muscle weakness and lactic acidosis after exercise. "One-carbon metabolism is altered in Sengers syndrome patient cells, owing to the perturbed biogenesis of the novel TIMM22 complex substrates, SFXN1, SFXN2 and SFXN3." (PMID 36475414, 2022).
heart failure (1 paper, 2020). Inability of the heart to pump blood at an adequate rate to meet tissue metabolic requirements. "Finally, CACNB2, KCNAB2, and TIMM22 encode subunits that participate in dysfunctional voltage-gated channels that may be associated with arrhythmia events rather than aggravated heart failure." (PMID 32802835, 2020).
oral cancer (1 paper, 2021). "After time course treatments of POMx, the mitochondrial resident protein (TIMM22 and TOMM20) expressions were detected in oral cancer cells." (PMID 34356350, 2021). "For 24 h POMx incubations, the TIMM22 and TOMM20 are almost unchanged in oral cancer cells." (PMID 34356350, 2021).
mitochondrial disease (2 papers, 2018 to 2022). "Two subunits of the TIMM22 complex are currently connected to mitochondrial disease: the pore subunit TIMM22, and the receptor subunit AGK (acylglycerol kinase)." (PMID 36475414, 2022).
TIMM22 also shares sentences with these, for which no sentence is quoted: cancer (3 papers); brain tumors (1); breast carcinoma (1); colon cancers (1); familial focal epilepsy (1); Mitochondrial myopathy (1); peripheral neuropathy (1).